TFF3 (trefoil factor 3)
Diseases named in the same sentence as TFF3 in open-access papers (continued):
Sharing a sentence is not in itself a finding about the gene and the disease.
Hepatic steatosis (5 papers, 2013 to 2025). Steatosis is a term used to denote lipid accumulation within hepatocytes. "Gene expression of Tff3 in the liver is significantly downregulated in different mouse models of obesity, diabesity and liver steatosis, conditions that are associated with ER dysfunction." (PMID 31500117, 2019). "Another study also implies that hepatic Tff3 expression levels are associated with hepatic steatosis." (PMID 24086476, 2013). "Previous studies found the overexpression of TFF3 in obese mice, while our Tff3-deficient mice fed an HFD also showed a reduction in liver steatosis." (PMID 40426854, 2025). "It appears that Tff3 deficiency in the whole organism (in the SD and HFD models) has protective effects with respect to metabolic health of the organism and reduces hepatic steatosis." (PMID 36013467, 2022). "Because we were interested in elucidating the effect of Tff3 deficiency in the case of metabolic syndrome conditions and liver steatosis, we further concentrated on the effects of HFD exposure in WT and Tff3-/- mice of both sexes." (PMID 36013467, 2022). "Given the relevance of inflammation in the pathophysiology of fatty liver disease, as well as the involvement of Tff3 protein in immune signalling, we analysed the gene expressions of the relevant inflammatory markers in the livers of the studied animals." (PMID 36013467, 2022). "In Tff3-/- mice, a marked reduction in hepatic steatosis was observed, especially in Tff3-/- males." (PMID 36013467, 2022). "Moreover, Tff3 was shown to directly bind to the promoter region of peroxisome proliferator-activated receptor alpha (Pparα) and upregulate its expression, which subsequently reduced hepatic steatosis by increasing the fatty oxidation process in the liver." (PMID 36013467, 2022). "Tff3-/-/C57Bl6N mice of both sex had reduced liver steatosis, without major fatty acid content perturbations." (PMID 36013467, 2022).
injury (5 papers, 2013 to 2025). Damage inflicted on the body as the direct or indirect result of an external force, with or without disruption of structural continuity. "In this present study, we evaluated the value of serum concentrations of biomarkers that have been identified as potential urinary biomarkers for VIKI (osteopontin, NGAL, clusterin) and other drug-induced kidney injury (trefoil factor-3 (TFF3)) for diagnosis of VIKI." (PMID 34768522, 2021). "Serum levels of TFF3 were significantly increased after skeletal trauma in humans." (PMID 31480518, 2019). "In contrast, larger series in adults have demonstrated that both serum and urine TFF3 levels increase with the progression of kidney injury, and elevated serum TFF3 in adults has also been associated with non-renal conditions such as inflammation, malignancy, and gastrointestinal disorders." (PMID 40868470, 2025).
lung carcinoma (5 papers, 2012 to 2025). "Immunoblot analyses of TFF1, TFF2 and TFF3 indicated that lung cancer tissues and lung cancer cell lines have higher expression levels of TFF3 protein, but not of TFF1 and TFF2 proteins, compared to tissues from healthy individuals or from normal cell line." (PMID 22246423, 2012). "We analyzed the correlation between the levels of serum TFF3 and the stages of the investigated 130 lung cancer patients using the statistical software." (PMID 22246423, 2012). "Immunoblot analyses of TFF1, TFF2 and TFF3 indicated that lung cancer tissues and lung cancer cell lines have a higher expression of the TFF3 protein, but not of TFF1 or TFF2 proteins, compared to tissues from healthy individuals or from the normal cell line." (PMID 22246423, 2012). "In the present study, TFF3 levels in the serum of lung cancer patients differed from those of healthy individuals, suggesting that TFF3 is a novel biomarker easy to be measured in the clinic." (PMID 22246423, 2012). "It was found that TFF1 and TFF2 have similar or slightly higher levels in these three subtypes of lung cancer compared to healthy individuals, while TFF3 levels were significantly higher in the examined lung cancer cases compared to healthy individuals." (PMID 22246423, 2012). "In this study, we investigated the protein and mRNA levels of TFF1, TFF2 and TFF3 in tissues of lung cancer patients and healthy individuals, and lung cancer cell lines and normal cell lines." (PMID 22246423, 2012). "It was found that among the three TFF proteins, the mRNA and protein levels of TFF3 in both cultured cell lines and tissues from patients have the best correlation with the development and prognosis of lung cancers." (PMID 22246423, 2012). "It was found that TFF1 and TFF2 levels were similar or slightly higher in these three subtypes of lung cancer compared to those in healthy individuals, while TFF3 levels were significantly higher in the detected lung cancer cases compared to healthy individuals." (PMID 22246423, 2012). "The increased levels of TFF3 in the serum of lung cancer patients may be related to the upregulated protein expression in lung tissues." (PMID 22246423, 2012). "However, levels of TFF3 in the three cancer cell lines were significantly higher than in the normal cell line NuLi-1, suggesting a different TFF3 expression in the detected lung cancer cell lines." (PMID 22246423, 2012). "However, the roles of TFF1, TFF2 and TFF3 are still unclear in the prediction and prognosis of lung cancer." (PMID 22246423, 2012). "Our results show increased TFF3 levels in the serum and lung tissues, suggesting that TFF3 may serve as a promising, easy to detect biomarker of lung cancer." (PMID 22246423, 2012). "However, levels of TFF3 transcripts in patients with all three types of lung cancer were significantly higher (P<0.05) than in lung tissues of healthy individuals, suggesting increased TFF3 mRNA levels in lung cancer patients in comparison to the healthy individuals." (PMID 22246423, 2012). "However, the levels of secreted TFF3 proteins in the serum of lung cancer patients (squamous cell lung carcinoma, 592.2±110.2; adenocarcinoma, 665.8±118.6; SCLC, 983.4±229.5) are significantly higher when compared with the levels in healthy individuals (230.7±46.9)." (PMID 22246423, 2012). "However, TFF3 transcript levels in the three cancer cell lines were significantly higher (P<0.05) than in the normal cell line NuLi-1, suggesting increased TFF3 mRNA levels in lung cancer cell lines in comparison to the normal cell lines." (PMID 22246423, 2012). "However, levels of TFF3 in patients of three types of lung cancer were significantly higher than in lung tissues of healthy individuals, suggesting a different TFF3 expression in lung cancer patients." (PMID 22246423, 2012). "Therefore, TFF3 may be a promising biomarker for lung cancer, but not appropriate for stage detection of lung cancer patients." (PMID 22246423, 2012).
lung carcinoma (continued). "Quantitative RT-PCR analysis indicated higher levels of TFF3, but not TFF1 and TFF2, transcripts in lung cancer tissues or cell lines." (PMID 22246423, 2012). "Quantitative RT-PCR analysis of TFF1, TFF2 and TFF3 transcripts in tissues and cell lines indicated higher levels of TFF3, but not of TFF1 and TFF2 transcripts in lung cancer tissues or cell lines when compared with those in tissues of healthy individuals and normal cells." (PMID 22246423, 2012).
necrotizing enterocolitis (5 papers, 2014 to 2024). Necrotizing enterocolitis (NEC) is a devastating disease that affects mostly the intestine of premature infants. "B. bifidum treatment of neonatal necrotizing enterocolitis (NEC) markedly reduced number of Tff3-positive cells to values seen in normal healthy controls." (PMID 39628866, 2024). "Additionally, in a rat model of neonatal necrotizing enterocolitis, the numbers of TFF3 positive cells were reduced to normal level after feeding with live Bifidobacterium bifidum." (PMID 31405107, 2019). "In a rat model of necrotizing enterocolitis (NEC), B. bifidum was shown to increase mucin and TFF3 expression and decrease the disease severity." (PMID 38045921, 2023).
ovarian carcinoma (5 papers, 2009 to 2022). A malignant neoplasm originating from the surface ovarian epithelium. "Elevated expression levels of TFF1 and TFF3 have been shown to correlate with changes in Ca125 (progression) and endocrine therapy response rates in ovarian cancer." (PMID 36818673, 2022). "on OC histotyping, the TFF3 gene was used to separate different epithelial ovarian cancer subtypes." (PMID 36818673, 2022). "Members of the TFF protein family have also been included in immunohistochemistry (IHC) algorithms for characterizing both special histotypes, e.g. TFF3 as a biomarker for ovarian carcinoma subtyping, as well as identifying carcinomas of unknown primary origin (CUP)." (PMID 36818673, 2022). "Therefore, the TFF1 and TFF3 biomarkers may provide healthcare professionals with tools to better subclassify OC by histotype, more efficiently predict patient clinical outcome, and improve the treatment decision-making process for ovarian cancer." (PMID 36818673, 2022). "Despite displaying distinct protein expression patterns in ovarian carcinoma, Pearson correlation analysis revealed recurrent co-expression between TFF1/TFF2 and TFF1/TFF3." (PMID 36818673, 2022).
papillary thyroid carcinoma (5 papers, 2004 to 2026). "TFF3 contributes to EMT in papillary thyroid carcinoma cells via the MAPK/ERK signaling." (PMID 31988090, 2020). "Targeting CCND1 and its OS-mediated regulatory pathways offers a promising therapeutic strategy for PTC.CCND1, oxidative stress, papillary thyroid carcinoma, single-cell RNA sequencing, SOX4, TFF3." (PMID 41646983, 2026). "Quantitative RT–PCR was performed (ADM3, HGD1, LGALS3, PLAB, TFF3, TG) in the needle wash-out of 156 FNAB of follicular adenoma (FA), adenomatous nodules, follicular and papillary thyroid cancers (TC) and normal thyroid tissues (NT)." (PMID 22223087, 2012).
retinoblastoma (5 papers, 2016 to 2022). A malignant tumor that originates in the nuclear layer of the retina. "In our study presented, TFF3 executes an anti-proliferative and pro-apoptotic effect, resembling the features of a tumor suppressor, and thus, one might hypothesize that loss of TFF3 expression might contribute to retinoblastoma tumorigenesis." (PMID 27626280, 2016). "In contrast, retinoblastoma cell lines, with low levels of TFF3 expression, exhibited hypermethylation of the TFF3 promoter in a DNA methyltransferase 1 dependent manner." (PMID 29100386, 2017). "In the study presented, we investigated the effect of TFF3 overexpression on growth, viability, migration and tumorigenicity of the human retinoblastoma cell lines Y-79, WERI-Rb1, RBL-13 and RBL-15." (PMID 27626280, 2016). "As revealed by WST-1 and TUNEL assays as well as DAPI and BrdU cell counts, recombinant human TFF3 significantly lowers retinoblastoma cell viability and increases apoptosis levels." (PMID 27626280, 2016). "We found forced TFF3 expression to lower RB cell growth, viability, and tumorigenicity and to induce a significant increase in cell death levels of retinoblastoma cell lines." (PMID 27626280, 2016). "First, we tested the effect of recombinant human TFF3 (rTFF3) on Y-79 retinoblastoma cell viability." (PMID 27626280, 2016). "The influence of TFF3 on retinoblastoma cell apoptosis, proliferation, growth and oncogenicity has, however, not been investigated so far." (PMID 27626280, 2016). "Blockage experiments using Boc-D-fmk, a broad-spectrum caspase inhibitor, revealed the involvement of caspases in TFF3 induced apoptosis in retinoblastoma cells." (PMID 27626280, 2016). "Blockage experiments using a broad-spectrum caspase inhibitor and capase-3 immunocytochemistry revealed the involvement of caspases in general and of caspase-3 in particular in TFF3 induced apoptosis in retinoblastoma cell lines." (PMID 27626280, 2016). "Soft agarose and in ovo chicken chorioallantoic membrane (CAM) assays revealed that TFF3 overexpression influences anchorage independent growth and significantly decreases the size of tumors forming from retinoblastoma cells." (PMID 27626280, 2016). "Stable, lentiviral TFF3 overexpression lowers retinoblastoma cell viability, proliferation and growth and significantly increases cell death in retinoblastoma cells." (PMID 27626280, 2016). "Our study demonstrates that forced TFF3 expression exerts a significant pro-apoptotic, anti-proliferative, and tumor suppressive effect in retinoblastoma cells, setting a starting point for new additive chemotherapeutic approaches in the treatment of retinoblastoma." (PMID 27626280, 2016). "However, TFF3 contrarily acts as a tumor suppressor in retinoblastoma." (PMID 35626334, 2022). "Summarizing our data show that in RB cell lines a significant pro-apoptotic, anti-proliferative, and tumor suppressive effect can be ascribed to TFF3, setting a new starting point for future additive chemotherapeutic approaches to reduce retinoblastoma tumor size." (PMID 27626280, 2016). "Also RB cell lines, established from patients`primary tumors, exhibit only trace amounts of TFF3, and most recently, we demonstrated that the expression of TFF3 in retinoblastoma cell lines is epigenetically down-regulated." (PMID 27626280, 2016). "In retinoblastoma, EMP1 might be the key target of tumor suppressor trefoil factor family peptide 3 (TFF3) signal transduction." (PMID 36217151, 2022).
retinoblastoma (continued). "In addition, we could recently show that TFF3 overexpression in four different RB cell lines has anti-proliferative and pro-apoptotic effects in vitro and leads to reduced tumor growth in vivo, supporting the notion of TFF3 as a tumor suppressor in retinoblastoma." (PMID 31450568, 2019). "Trefoil factor family peptide 3 (TFF3) is supposed to have tumor suppressive functions in retinoblastoma (RB), but the functional pathway is not completely understood." (PMID 31450568, 2019). "Along this line our study revealed, that compared to the healthy human retina TFF3 mRNA (data not shown) and TFF3 protein expression levels are likewise below detection levels in primary retinoblastoma samples." (PMID 27626280, 2016). "We could demonstrate that the expression of TFF3 in retinoblastoma cell lines is regulated epigenetically and that forced TFF3 expression leads to reduced RB tumor growth, viability and tumorigenicity as well as enhanced caspase-dependent apoptosis induction in human RB cell lines." (PMID 31450568, 2019). "Taken together, our data strengthen the tumor suppressive function of TFF3 in retinoblastoma cells and emphasize TFF3’s downstream signaling components miR-34a and EMP1 as potential targets for adjuvant RB therapy and drug development strategies." (PMID 31450568, 2019).
Sepsis (5 papers, 2020 to 2026). Sepsis is defined as life-threatening organ dysfunction caused by a dysregulated host response to infection. "• Elevated TFF3 levels were associated with poor outcomes and independently predicted sepsis severity and gastrointestinal dysfunction in critically ill children." (PMID 42154329, 2026). "In patients with sepsis, TFF3 levels were associated with kidney injury, multiorgan dysfunction, and mortality." (PMID 36069443, 2022). "The high serum TFF-3 was described also in the association with the severity, multiple organ dysfunctions, and prognosis of sepsis patients." (PMID 32190704, 2020). "The purpose of this study is to evaluate trefoil factor 3 (TFF3) as a biomarker of gastrointestinal cellular injury in children with sepsis." (PMID 42154329, 2026). "TFF3 levels were markedly elevated in sepsis with gastrointestinal involvement compared to sepsis without gastrointestinal involvement and controls (P < 0.001)." (PMID 42154329, 2026). "In the multinomial logistic regression analysis using the control group as the reference category, TFF3 emerged as a significant predictor of sepsis outcomes." (PMID 42154329, 2026). "Citrulline levels are correlated strongly with small bowel length and disease activity in various (chronic) enteropathies, and conversely to I-FABP and TFF-3, are known to decrease in critical illness and sepsis." (PMID 38536623, 2024). "Thus, we can speculate that increased TFF-3 in sepsis could be a secondary phenomenon caused by the blood redistribution leading to the gut barrier dysfunction, which in turn can contribute to the development of uncontrolled systemic inflammatory response syndrome." (PMID 32190704, 2020). "For patients with sepsis without gastrointestinal involvement, higher TFF3 levels were significantly associated with increased odds of sepsis (OR = 1.814, 95% CI 1.282-2.567, P = 0.001)." (PMID 42154329, 2026). "TFF-3 is elevated in patients with severe sepsis and inflammatory bowel diseases." (PMID 32190704, 2020). "During the first 6 hours after the enrolment, infants who will later develop NEC (NEC group) had significantly higher urinary I-FABP, L-FABP, TFF-3, and SAA when compared with healthy infants and higher levels of I-FABP and L-FABP than those who will later develop sepsis (sepsis group)." (PMID 32190704, 2020).
chronic periodontitis (4 papers, 2017 to 2024). A chronic inflammatory process that affects the tissues that surround and support the teeth. "TFF3 levels in the serumof gingivitis and periodontitis patients differed from pre operatively to post operatively suggesting that TFF3 is a novel biomarkereasy to be measured in the clinic." (PMID 39917209, 2024). "Salivary TFF1 and TFF3 concentrations are reduced in patients with chronic periodontitis, whereas salivary TFF3 is elevated in children with oral mucositis." (PMID 34830103, 2021). "Chaiyarit and co-workers examined TFF peptides in the gingival tissues of patients with chronic periodontitis and found a significantly reduced TFF3 concentration in pathologically altered tissue samples." (PMID 29028798, 2017). "Therefore, it is of interest to measure serum trefoil factor 3 at baseline and 3 months after followingnonsurgical periodontal therapy in patients with Gingivitis and Chronic Periodontitis." (PMID 39917209, 2024). "The authors speculate that, in chronic periodontitis, bacteria may influence the TFF3 expression negatively." (PMID 29028798, 2017). "Increased serum TFF3 concentrations were observedafter non-surgical periodontal therapy in both gingivitis and chronic periodontitis group (p<0.001)." (PMID 39917209, 2024). "In our study 40 patients with gingivitis and periodontitis with moderate disease activity were enrolled and evaluated forserum TFF3 after Non-surgical periodontal therapy." (PMID 39917209, 2024).
cognitive decline (4 papers, 2014 to 2024). "Low CSF TFF3 levels are associated with both the rate of cognitive decline and the rate of hippocampal atrophy and ventricular expansion." (PMID 29392081, 2018). "In particular, our results suggest that in individuals with evidence for brain amyloid deposition, CSF TFF3 level is associated both with rate of cognitive decline and with rates of brain and hippocampal atrophy and ventricular expansion." (PMID 25072324, 2014). "Trefoil factor 3 (TFF3), a substrate of NOTCH signaling, may also serve as a candidate CSF marker for cognitive decline." (PMID 31450692, 2019).